RN7SL854P (RNA, 7SL, cytoplasmic 854, pseudogene)
Gene: Miscellaneous RNA gene on chromosome 1 (65,761,058 to 65,761,352, reverse strand). Ensembl gene ENSG00000239319.
Homologues: Orthologues: chimpanzee Metazoa_SRP (99% identical), macaque Metazoa_SRP (93% identical). Paralogues in human: RN7SL1 (80% identical), RN7SL2 (80% identical), RN7SL3 (79% identical), RN7SL296P (78% identical), RN7SL326P (78% identical), RN7SL660P (78% identical), RN7SL7P (78% identical), RN7SL300P (77% identical), RN7SL558P (77% identical), RN7SL14P (77% identical), RN7SL183P (77% identical), RN7SL126P (76% identical), and 703 more.